MIR6894 (microRNA 6894)
Synonyms: hsa-mir-6894
Gene: MicroRNA gene on chromosome X (53,198,889 to 53,198,945, reverse strand). Ensembl gene ENSG00000277474.
Homologues: Orthologues: chimpanzee MIR6894 (100% identical).